LILRB4 (leukocyte immunoglobulin like receptor B4)
Diseases named in the same sentence as LILRB4 in open-access papers (continued):
Sharing a sentence is not in itself a finding about the gene and the disease.
multiple myeloma (continued). "The CM from J558-LILRB4 cells could significantly induce osteoclastogenesis when compared with the CM from J558-vector cells, suggesting that LILRB4 on multiple myeloma cells could induce osteoclastogenesis." (PMID 38951916, 2024). "Xenograft, syngeneic and patient derived xenograft models furtherly confirmed that LILRB4 could mediate bone lesion of multiple myeloma." (PMID 38951916, 2024). "Next, we confirmed that LILRB4 could recruit p-SHP2 in multiple myeloma cells by Co-IP, and the co-transfection of p65 could significantly promote the activity of dual luciferase reporter system." (PMID 38951916, 2024). "Our results suggested that LILRB4 was highly expressed in multiple myeloma cells." (PMID 38951916, 2024). "The deletion of LILRB4, anti-LILRB4 alone or in combination with bortezomib could significantly delay the progression of bone lesion of multiple myeloma." (PMID 38951916, 2024). "We found that knockdown of the expression of LILRB4 could significantly increase the chemosensitivity of multiple myeloma cells, as evidenced by a synergistically effect in suppression of cell proliferation." (PMID 39025844, 2024). "The depletion of LILRB4 or anti-LILRB4 alone or in combination with BTZ could delay the progression of multiple myeloma, and significantly inhibit the bone damage." (PMID 38951916, 2024). "Collectively, ectopic LILRB4 significantly promoted bone lesion of multiple myeloma." (PMID 38951916, 2024). "Subsequently, we explored the mechanism of LILRB4 promoting bone injury in multiple myeloma." (PMID 38951916, 2024). "Similarly, an increased concentration of LILRB4 in cell culture supernatant was observed when myeloma cells were co-cocultured with BM aspirates compared with monocultured BM aspirates." (PMID 39696628, 2024). "The deletion of LILRB4 or anti-LILRB4 combined with bortezomib (BTZ) could significantly delay the progression of bone lesion of multiple myeloma." (PMID 38951916, 2024). "Next, we used different animal models to study whether LILRB4 in multiple myeloma can mediate osteolytic lesions." (PMID 38951916, 2024). "LILRB4 is expressed in a subset of highly aggressive multiple myeloma (MM) variants and may not be sufficient to rapidly resolve the disease in clinical therapy." (PMID 41417876, 2025). "Moreover, LILRB4 was also expressed in multiple myeloma cell lines KMS26 and OPM2." (PMID 38951916, 2024). "It is unclear whether ectopic LILRB4 on multiple myeloma regulates bone lesion." (PMID 38951916, 2024). "Finally, we tried to explore the role of LILRB4 in treatment of multiple myeloma." (PMID 38951916, 2024). "In multiple myeloma (MM), the transcription factor Ikaros family zinc finger protein 1 (IKZF1) directly activated LILRB4 transcription." (PMID 40860159, 2025). "Mechanistically, LILRB4 recruited phosphorylated SHP2 to activate NF-κB signaling, promoting multiple myeloma cells to secret RELT." (PMID 40860159, 2025). "Mechanistically, fibronectin or apoE binding to LILRB4 recruited p-SHP2 to activate NF-κB signal pathway, then promoted multiple myeloma cells to secret RELT." (PMID 38951916, 2024). "CD45−/CD38+/LILRB4+ and CD45−/CD38+/LILRB4− myeloma cells from the same patient were sorted, and the same number of cells were injected into NSG mice by intratibial injection, respectively." (PMID 38951916, 2024). "However, it is unknown whether LILRB4 is functional in myeloma pathogenesis." (PMID 38951916, 2024). "Leukocyte immunoglobulin‐like receptor B4 (LILRB4), a member of the LILR family located on 19q13.4, facilitates immune evasion in various cancers, including multiple myeloma, lung cancer and gastric cancer, by interacting with immune cells within the tumour microenvironment." (PMID 40576161, 2025). "Although LILRB4 expressed on the surface of osteoclast negatively regulated osteoclastogenesis, the role of LILRB4 on bone lesion of multiple myeloma has not been reported." (PMID 38951916, 2024).
multiple myeloma (continued). "Meanwhile, the knockout of LILRB4 did not alter the proliferation of KMS26 and OPM2 cells, indicating that LILRB4 did not regulate the proliferation of multiple myeloma." (PMID 38951916, 2024). "Notably, we identified peptides from LILRB4, GGT1, and CCR10, further validating expression of surface markers on primary myeloma cells that we initially highlighted from cell line analysis." (PMID 35840578, 2022). "It was reported that ectopic LILRB4 in B-cell chronic lymphocytic leukemia was involved in the infiltration of lymphoid tissues, controlled the progression by suppressing the Akt pathway, but the role of LILRB4 in multiple myeloma has not been reported." (PMID 38951916, 2024). "It has not been reported whether LILRB4 on multiple myeloma cells is involved in osteoclastogenesis." (PMID 38951916, 2024). "After 14 days of CM treatment, the cellular boundary was unclear, the morphology disappeared, and the apoptosis was obvious, indicating the CM from multiple myeloma, whether LILRB4 was knocked out or not, could induce the apoptosis of osteoblasts." (PMID 38951916, 2024). "LILRB4 did not affect the proliferation and metastasis of multiple myeloma, but LILRB4 blocking antibody could prevent the binding of LILRB4 to its ligands, therefore, anti-LILRB4 could block its signal pathway to inhibit the RELT secretion, then alleviate bone damage." (PMID 38951916, 2024).
lung cancer (6 papers, 2018 to 2025). A malignant neoplasm involving the lung. "In lung cancer, LILRB4 directly activates ERK1/2 signalling, which mediates EMT and promotes tumour angiogenesis through recruitment of SHP2 and SHIP1." (PMID 40576161, 2025). "Because which types of leukocytes expressed LILRB4 in human lung were not clarified, we first examined the expression of LILRB4 on each type of leukocyte in single cell suspensions of normal lung tissue from the patients who received pneumonectomy for lung cancer." (PMID 34425800, 2021).
Alzheimer disease (5 papers, 2019 to 2025). A progressive, neurodegenerative disease characterized by loss of function and death of nerve cells in several areas of the brain leading to loss of cognitive function such as memory and language. "Upregulation of LILRB4 expression in the brain was described in microglia of aged mice as well as surrounding the plaques in a mouse model of Alzheimer’s disease, and its expression was associated with an immune suppressive/tolerizing function." (PMID 35132958, 2022). "Genome-wide association studies of late-onset Alzheimer’s disease risk predicted OAS1, LAPTM5, ITGAM/CD11b and LILRB4 as four new risk genes for this neurodegenerative disease." (PMID 34943215, 2021). "Our study supposes that LILRB4 may play a crucial role in modulating PD clinical characteristics by influencing nigrostriatal dopaminergic neuron function, Alzheimer's disease (AD)‐related pathology, WM microstructural alterations, and astrocyte activation." (PMID 40702763, 2025). "These four genes, OAS1, LAPTM5, ITGAM/CD11b and LILRB4, have not been previously reported as having variants significantly associated with Alzheimer’s disease using traditional GWAS approaches." (PMID 32274467, 2019). "Given the previous studies for ITGAM/CD11b, LAPTM5 and LILRB4, it is tempting to speculate that they are involved in phagocytic processes involving synapses which are known to be reactivated during Alzheimer’s disease progression." (PMID 32274467, 2019).
colorectal cancer (5 papers, 2019 to 2025). A primary or metastatic malignant neoplasm that affects the colon or rectum. "Under physiological conditions, LILRB4 expression is highly restricted to these cell types; however, its overexpression has been observed in various malignancies, including advanced-stage colorectal cancer, non-small-cell lung cancer, and ovarian tumors." (PMID 40597436, 2025). "LILRB4 also exists in a soluble form detected in the serum of patients with pancreatic carcinoma, colorectal cancer, and melanoma." (PMID 40597436, 2025).
multiple sclerosis (5 papers, 2013 to 2025). A progressive autoimmune disorder affecting the central nervous system resulting in demyelination. "One study demonstrated that LILRB4 expression on monocytes in patients with multiple sclerosis can be upregulated upon stimulation with Vitamin D3 and IFN-γ." (PMID 34276685, 2021). "Similarly, elevated LILRB4 expression has been detected in cerebral WM demyelinating lesions in patients with multiple sclerosis (MS)." (PMID 40702763, 2025). "In addition, abnormal LILRB4 correlates significantly with inflammatory diseases, such as multiple sclerosis and inflammatory bowel disease." (PMID 38971897, 2024). "Vitamin D3 and IFN-γ could therefore be useful in patients with multiple sclerosis to reduce the cerebral inflammation in a LILRB4 dependent fashion." (PMID 34276685, 2021).
COVID-19 (4 papers, 2021 to 2024). A disease caused by infection with severe acute respiratory syndrome coronavirus 2. "This extensive proteomic analysis unbiasedly identified IL6 and five novel proteins (CKAP4, Gal-9, IL-1ra, LILRB4 and PD-L1) to be associated with disease severity in COVID-19 cases." (PMID 33737684, 2021). "It is important to note that our putative biomarkers of disease progression in COVID-19 (IL6, CKAP4, Gal-9, IL-1ra, LILRB4 and PD-L1) were associated to NfL but to a much lesser extent to GFAP and tau." (PMID 33737684, 2021). "LILRB4 represents a compelling target to investigate COVID-19 treatment." (PMID 33737684, 2021).
pancreatic cancer (4 papers, 2019 to 2024). "LILRB4 was associated with impaired T cell responses in pancreatic cancer, and antagonistic LILRB4 was the key to successful immunotherapy." (PMID 36748687, 2023). "To further analyze the expression pattern of LILRB4 within tumor-infiltrating T cell subsets, we analyzed LILRB4 expression in various murine tumor models, including B16/F10, pancreatic tumor model mT5, colon carcinoma model MC38, and bladder cancer model MB49." (PMID 33974041, 2021). "We hypothesized that LILRB4 could play an important role in tumor immunity on the basis of our expression results, which showed LILRB4 expression in various solid tumors, including so-called cold tumors like pancreatic tumors, and high correlation with various inhibitory receptors." (PMID 33974041, 2021).
prostate carcinoma (4 papers, 2021 to 2025). A carcinoma that arises from epithelial cells of the prostate gland. "We found a similar pattern of expression of LILRB4 in the TRAMP-C2 prostate cancer model, where the expression of LILRB4 was higher on CD4+ T cells than on CD8+ T cells." (PMID 33974041, 2021). "Because these nonspontaneous tumor models do not recapitulate the full process of oncogenesis, we decided to analyze LILRB4 expression in TRAMP mice, a spontaneous model of prostate cancer, where we compared the expression of LILRB4 on naive prostate to the TRAMP mice prostate." (PMID 33974041, 2021).
viral infection (4 papers, 2011 to 2024). "LILRB4 controls viral load in viral infections by ensuring normal cell maturation and function of NK cells, resulting in effective viral clearance and patient survival." (PMID 38397424, 2024). "Nevertheless, this is probably the first paper suggesting the virus as the ligand for human and mouse LILRB4 and suggesting a clinical relevance for the mouse system in investigating the role of LILRB4 in controlling viral infection in humans." (PMID 35132958, 2022). "Our study describes a biological role for LILRB4 as a mediator of effective NK cell maturation and activation during a viral infection in mice." (PMID 35132958, 2022). "Together, our data reveal LILRB4/gp49B as an important regulator of NK cell function during viral infections." (PMID 35132958, 2022). "We also summarized the role of LILRB4 in numerous disease processes, such as viral infection and inflammatory diseases, which suggests that LILRB4 may be a relevant target molecule in many kinds of diseases, signifying its broad research prospects." (PMID 38397424, 2024). "In viral infections, LILRB4 usually acts positively to control viral infections." (PMID 38397424, 2024). "Increased expression of anotherinhibitory ILT, LILRB4 or ILT3, also impairs antigen presentationand T cell recruitment as well as modulates the expression of proinflammatorycytokines.Together, these transcriptional changes observed in immune response genes areconsistent with viral infection." (PMID 21359205, 2011). "However, the role of LILRB4 in regulating the response to viral infection is mostly unknown." (PMID 35132958, 2022). "Purified mouse LILRB4 (mLILRB4) proteins, as well as human LILRB4 (hLILRB4) proteins, bind to ZIKV directly in a dose-dependent manner, whereas LILRA5 does not, suggesting that LILRB4 could directly modulate viral infection of cells." (PMID 35132958, 2022).
B-cell chronic lymphocytic leukemia (3 papers, 2024 to 2025). "LILRB2 and LILRB4 were demonstrated to be specific biomarkers of chronic lymphocytic leukemia (CLL) and show consistent expression patterns between the two receptors." (PMID 39696628, 2024). "Additionally, LILRB4 expression correlated with lymphoid tissue involvement in CLL/small lymphocytic lymphoma (SLL), a prognostic indicator of poor outcomes." (PMID 39696628, 2024). "Moreover, LILRB4 may contribute to chronic lymphocytic leukaemia progression by regulating the AKT pathway." (PMID 40576161, 2025).
breast cancer (3 papers, 2021 to 2025). A primary or metastatic malignant neoplasm involving the breast. "We further demonstrated that CRD enhanced the expression of LILRB4 in vivo in healthy mammary glands and mammary tumors." (PMID 41102383, 2025). "The CD8 infiltration decreased, whereas M2-like macrophage populations (CD163) increased along with LILRB4 in CRD-induced mammary tumors, as shown using MxIF." (PMID 41102383, 2025). "We found that the disruption of circadian rhythm upregulated LILRB4 expression, which correlated with mammary tumor progression and abnormal morphology in the mammary glands." (PMID 41102383, 2025). "Breast cancer, lung squamous cell carcinoma, and lung adenocarcinoma showed a significantly higher LILRB4/CD3ε mRNA expression ratio in tumor samples than normal tissue samples." (PMID 33974041, 2021). "LILRB4 expression was increased in mammary glands and CRD-induced mammary tumors, revealing an unidentified mechanism responsible for CRD-induced tumorigenesis, lung metastasis, and mammary gland abnormality." (PMID 41102383, 2025).
non-small cell lung carcinoma (3 papers, 2023 to 2024). A group of at least three distinct histological types of lung cancer, including non-small cell squamous cell carcinoma, adenocarcinoma, and large cell carcinoma. "In addition, LILRB4 has been reported to be expressed in non-small cell lung cancer, therefore, elucidating the expression pattern of LILRB4 in tumor cells is fundamental for investigating the role of LILRB4." (PMID 38951916, 2024). "In non-small cell lung cancer (NSCLC), LILRB4 enrichment in tumor cells is often predictive of advanced disease progression and poorer overall survival." (PMID 38397424, 2024).
nonalcoholic fatty liver disease (3 papers, 2019 to 2024). "In a mouse model of nonalcoholic fatty liver disease, overexpression of LILRB4 largely reversed intrinsic hepatic steatosis, inflammation and metabolic disturbances." (PMID 38397424, 2024). "It has been reported that LILRB4 are involved in the pathogenesis of various diseases such as allergic diseases, acute lung injury, cancer, autoimmune diseases, transplantation immunity, nonalcoholic fatty liver disease, and infection disease." (PMID 34425800, 2021). "A previous report showed that LILRB4 is upregulated on hepatocytes in nonalcoholic fatty liver disease (NAFLD), a chronic inflammatory disease of the liver." (PMID 34425800, 2021). "LILRB4 inhibits the expression of TRAF6 and downstream inflammatory factors, thereby inhibiting the occurrence and development of non-alcoholic fatty liver disease." (PMID 31138763, 2019).
Salmonella Infections (3 papers, 2009 to 2019). Infections with bacteria of the genus SALMONELLA. "Regarding infectious diseases, Salmonella infection sufficiently enhances LILRB4 expression on DCs and monocytes and its activation results in increased levels of IL-10 production." (PMID 31849951, 2019). "In human cells the inhibitory receptors LILRB2 and LILRB4 were upregulated following Salmonella infection, an effect which appears to be mediated largely by LPS recognition, as activation of LILRB4 also occurred by both heat-inactivated Salmonella and Salmonella LPS." (PMID 20634939, 2010). "To address this, we observed the effects of Salmonella infection on LILRB2 and LILRB4 expression." (PMID 19860908, 2009).
Skin cutaneous melanoma (3 papers, 2007 to 2024). "Skin cutaneous melanoma and bladder cancer (data not shown), although not significant, showed a trend of higher LILRB4 compared with normal tissue." (PMID 33974041, 2021).